SNHG3 (small nucleolar RNA host gene 3)
Synonyms: U17HG; U17HG-A; NCRNA00014; RNU17C; RNU17D; U17HG-AB
Gene: Long non-coding RNA gene on chromosome 1 (28,505,980 to 28,510,892, forward strand). Ensembl gene ENSG00000242125.
Diseases named in the same sentence as SNHG3 in open-access papers:
SNHG3 is named in the same sentence as 60 diseases in open-access papers, as found by Europe PMC text mining. Sharing a sentence is not in itself a finding about the gene and the disease. The quoted sentences say what the papers report.
hepatocellular carcinoma (37 papers, 2017 to 2025). A malignant tumor that arises from hepatocytes. "In hepatocellular carcinoma patients, associations between increased SNHG3 levels with malignant status and poor prognosis have been reported." (PMID 35704638, 2022). "SNHG3 is up-regulated in ovarian cancer, glioma, hepatocellular carcinoma, and osteosarcoma, all of which are associated with poor prognosis." (PMID 36387240, 2022). "SNHG3 was overexpressed in colorectal cancer, ovarian cancer, osteosarcoma and hepatocellular carcinoma, and its upregulation was associated with poor OS." (PMID 32126023, 2020). "The clinical data also suggested an unrecognized association between high SNHG3 and tumor metastasis, which was consistent with Zhang’s conclusion in hepatocellular carcinoma wherein SNHG3 induced EMT processing via modulating the miR-128/CD151 signaling." (PMID 31534128, 2019). "Increased SNHG3 expression is associated with malignant status and worse overall survival, recurrence-free survival and disease-free survival in hepatocellular carcinoma patients." (PMID 28738804, 2017). "SNHG3 in our data is mostly cytoplasmic in H1.hESC, HepG2 (liver carcinoma) and GM12878 (lymphoblast) cells, but nuclear in cell-lines like MCF-7 and NHEK." (PMID 40491847, 2025). "SNHG3 is known to block apoptosis in various cancers like gastric cancer, glioma, hepatocellular carcinoma, laryngeal squamous cell carcinoma, lung cancer, and prostate cancer." (PMID 41042421, 2025). "Increasing evidence suggests that SNHG3 plays a carcinogenic role in multiple cancers, including breast cancer, osteosarcoma, hepatocellular carcinoma, gastric cancer, colorectal cancer, and so forth 33, 35-38." (PMID 38725844, 2024). "This study further found that SNHG3 overexpression induced EMT in hepatoma cells through miR‐128/CD151 cascade activation." (PMID 36420693, 2023). "Recent studies have shown that SNHG3 expression is higher in many tumors, such as osteosarcoma, breast cancer and hepatocellular carcinoma." (PMID 36727055, 2022). "Recently, it was found that the expression of SNHG3 was significantly higher in hepatocellular carcinoma than in paracancerous tissues." (PMID 34991609, 2022). "SNHG3 is a newly found lncRNA and was discovered as a biomarker of malignant cancers, for example, ovarian cancer, hepatocellular carcinoma, colorectal cancer, lung cancer, and glioma." (PMID 34335693, 2021). "SNHG3 is overexpressed in hepatocellular carcinoma (HCC), showing correlation with the survival of HCC patients." (PMID 33869776, 2021). "Previous study suggested that lncRNA small nucleolar RNA host gene 3 (SNHG3) acted as an oncogene in the progression of various cancers, including hepatocellular carcinoma, colorectal cancer and lung cancer." (PMID 32596993, 2020). "For instance, up‐regulated lncRNA SNHG3 is connected to the serious progression and poor prognosis of hepatocellular carcinoma." (PMID 32248648, 2020). "For example, increased SNHG3 expression is correlated with poor prognosis and sorafenib resistance in hepatocellular carcinoma (HCC)." (PMID 31581131, 2019). "A previous study in hepatocellular carcinoma showed that the expression of SNHG3 was overexpressed in cancer cells." (PMID 30154938, 2018). "In the previous study, SNHG3 was found to be overexpressed in hepatocellular carcinoma, showing that SNHG3 acted as an oncogene." (PMID 30154938, 2018). "A previous study on hepatocellular carcinoma showed that the expression of SNHG3 was overexpressed in cancer cells." (PMID 30154938, 2018). "Also, lncRNA small nucleolar RNA host gene 3 (SNHG3) has been identified as oncogene in many cancers, such as hepatocellular carcinoma, colorectal cancer, glioma, ovarian cancer, and osteosarcoma." (PMID 32248648, 2020).
hepatocellular carcinoma (continued). "The results demonstrated that overexpressed SNHG3 was significantly associated with poor OS in various cancers (HR = 2.53, 95% CI: 1.94-3.31) and poor DFS (HR = 3.89, 95% CI: 1.34-11.3) and RFS (HR = 2.42, 95% CI: 1.14-5.15) in hepatocellular carcinoma." (PMID 32802874, 2020). "For instance, in hepatocellular carcinoma (HCC), SNHG3 regulates NEIL3 expression through transcription factor E2F1, implicating it as a potential diagnostic marker and therapeutic target." (PMID 39349640, 2024). "This section highlights the pivotal role of lncrna SNHG3's cerna mechanism in promoting cancer progression across various types, exemplified particularly in hepatocellular carcinoma (HCC)." (PMID 39349640, 2024). "In hepatocellular carcinoma (HCC), SNHG3 regulates proliferation and migration through the SNHG3/miR-139-5p/BMI1 axis." (PMID 39349640, 2024). "Exploring SNHG3's role in hepatocellular carcinoma (HCC), the study identified elevated expression in highly metastatic HCC cells." (PMID 39349640, 2024). "In addition, STEAP3-AS1 also displayed an oncogenic role in human hepatocellular carcinoma (HCC) by acting as a competing endogenous RNA (ceRNA) and served as a risk scoring system together with three other lncRNAs (SNHG1, RUSC1-AS1, and SNHG3) to predict the outcomes of HCC patients." (PMID 35986274, 2022). "Previous studies reported that SNHG3 is upregulated in cancers and may act as an oncogene in tumor prognosis, including osteosarcoma, glioma, ovarian cancers, breast cancer, and hepatocellular carcinoma." (PMID 32802874, 2020). "Small nucleolar RNA host gene 3 (Snhg3) is a newly discovered lncRNA that was identified as a biomarker of malignant status or poor prognosis in several types of cancers including lung cancer, hepatocellular carcinoma, glioma, ovarian cancer, and colorectal cancer." (PMID 31151411, 2019). "In conclusion, SNHG3 was selected as a possible upstream lncRNA for miR-139-5p, thereby affecting the LPCAT1 expression and promoting hepatocellular carcinoma progression." (PMID 35615532, 2022). "The SNHG3 and THUMPD3-AS1/hsa-miR-139-5p-SLC52A2 axis were identified as potential regulatory pathways in hepatocellular carcinoma." (PMID 34991609, 2022). "LncRNA SNHG3 also was characterized to be involved in the microRNA pathway in hepatocellular carcinoma, wherein the modulation of miR-128/CD151 signaling by SNHG3 induced epithelial-mesenchymal transition (EMT) and sorafenib resistance." (PMID 31534128, 2019). "SNHG3 is overexpressed in hepatocellular carcinoma (HCC) tissues in contrast with the matched non-malignant tissues." (PMID 33859998, 2021). "In addition, SNHG3 acts as a ceRNA and induces EMT in hepatoma cells via the miR128/CD151 signaling pathway." (PMID 33292213, 2020). "Similarly, SNHG3 repressed the degradation of CD151 by competing with miR-128, contributing to the epithelial–mesenchymal transition (EMT) and sorafenib resistance in hepatocellular carcinoma." (PMID 33817254, 2020). "It is reported that SNHG3 is significantly up-regulated in hepatocellular carcinoma (HCC) compared with paired non-tumor tissues; up-regulation of SNHG3 is correlated with overall survival, recurrence-free survival and relapse in HCC." (PMID 28484081, 2017).
colorectal cancer (29 papers, 2019 to 2025). A primary or metastatic malignant neoplasm that affects the colon or rectum. "The expression of SNHG3 is up-regulated in colorectal cancer tissues and cell lines, and its high level is associated with advanced colorectal cancer stage, positive lymph node metastasis and poor prognosis." (PMID 39830506, 2024). "lncRNA SNHG3 is reported to be implicated in development of various types of cancers, such as colorectal cancer and ovarian cancer." (PMID 33869776, 2021). "It was reported that SNHG3 was overexpressed in liver cancer, breast cancer, and colorectal cancer, which was associated with poor survival and prognosis in tumor-bearing patients." (PMID 31956955, 2020). "SNHG3 is a novel lncRNA potentially associated with various cancers, including lung adenocarcinoma, ovarian cancer, osteosarcoma, renal cell carcinoma, colorectal cancer and some other cancers 12,13,22-24." (PMID 32284745, 2020). "Studies in other cancers have reported similar results; high expression of SNHG3 was found to be significantly associated with poor prognosis in gastric cancer, osteosarcoma, laryngeal carcinoma, non-small-cell lung cancer, and colorectal cancer." (PMID 34336642, 2021). "In addition, alteration of SNHG3 expression is associated with the onset of many cancers, for example, SNHG3 functioned as ceRNA by sponging miR-182-5p to release c-Myc and promote malignant development in colorectal cancer." (PMID 33817254, 2020). "CAF-EVs facilitated colorectal cancer cell proliferation by transferring SNHG3 into colorectal cancer cells, increasing SNHG3 expression." (PMID 41042421, 2025). "In colorectal cancer, SNHG3 expression levels in CAFs and CAF-derived extracellular vesicles (EVs) were higher than in normal fibroblasts (NFs) and NF-EVs." (PMID 41042421, 2025). "For example, some lncRNAs, such as cancer susceptibility candidate 9 (CASC9), POU3F3, small nucleolar RNA host gene 3 (SNHG3), CDKN2B-AS1 (ANRIL), colorectal cancer-associated lncRNA (CCAL), and ZEB2-AS1 (ZEB2NAT), are upregulated in CAFs." (PMID 37190145, 2023). "For instance, SNHG3 can serve as a ceRNA to exacerbate colorectal cancer malignant progression through the miR-182-5p/c-Myc axis." (PMID 35123415, 2022). "SNHG3 was identified as a competitive endogenous RNA molecule to promote the malignant progression of colorectal cancer." (PMID 34257656, 2021). "SNHG3 can function as a ceRNA by acting as miR‐182‐5p sponge to indirectly regulate expression of mRNAs and aggravate the progression of colorectal cancer." (PMID 32248648, 2020). "Small Nucleolar RNA Host Gene 3 (SNHG3) is a novel lncRNA potentially associated with Alzheimer disease and colorectal cancer." (PMID 31534128, 2019). "This phenomenon is exemplified in various cancers: WEE2-AS1 and SNHG3 in colorectal cancer; NEAT1 in endometrial cancer; LINC00355 in bladder cancer; SNHG3 in breast cancer; TUC338 in laryngeal squamous cell carcinoma; FTX in oral squamous cell carcinoma; and NNT-AS1 in pancreatic cancer." (PMID 39717771, 2024). "Accumulating evidence demonstrates that the expression of SNHG3 was increased in variety types of tumor tissues such as breast cancer, hepatocellular carcinoma, and colorectal cancer, resulting in increased proliferation and metastasis of tumor cells and poor survival of tumor-bearing patients." (PMID 31956955, 2020). "Additionally, animal models with tumors showed that reducing SNHG3 led to smaller tumor volume and weight, including bladder cancer, breast cancer, colorectal cancer, gastric cancer, glioma, laryngeal squamous cell carcinoma, ovarian cancer, papillary thyroid carcinoma, and prostate cancer." (PMID 41042421, 2025). "SNHG3 is a new type of lncRNA, which may be related to Alzheimer's disease and colorectal cancer." (PMID 34257656, 2021). "In colorectal cancer cell lines (e.g., SW480, LoVo), SNHG3 was found to localize predominantly in the cytoplasm (comparable to GAPDH)." (PMID 40491847, 2025).
colorectal cancer (continued). "In a study investigating the role of the long non-coding RNA (lncRNA) SNHG3 in colorectal cancer (CRC) progression, SNHG3 was found upregulated and correlated with advanced tumor stages, lymph node metastasis, and poor prognosis." (PMID 39349640, 2024). "CAFs produce SNHG3, which mitigates the degradative effect of miR-34b-5p on HuR, enhancing the stability of HOXC6 mRNA and thus fueling the proliferation of colorectal cancer cells." (PMID 39717771, 2024). "SNHG1, SNHG3, and SNHG20 are predictive biomarkers for neuroblastoma, ovarian cancer, and colorectal cancer, respectively." (PMID 35686101, 2022). "SNHG1, SNHG3, SNHG20 have been separately proved to be a prognostic biomarker in neuroblastoma, ovarian cancer, and colorectal cancer." (PMID 31967298, 2020). "Among the prognosis-related lncRNAs in HCC, SNHG3, SNHG4, and NRAV have been reported to function in bladder cancer, non-small cell lung cancer, osteosarcoma, colorectal cancer, breast cancer, gastric cancer, and glioma through interactive molecular pathway studies." (PMID 35734590, 2022).
breast cancer (26 papers, 2020 to 2025). A primary or metastatic malignant neoplasm involving the breast. "SNHG3 expression is abnormally elevated in cancer-associated fibroblasts (CAFs) from breast cancer patients compared to normal breast cells." (PMID 41042421, 2025). "We found that SNHG3 expression was upregulated in breast cancer tissues and that its high expression level was associated with poor survival." (PMID 37348024, 2023). "What is more, it was found that the level of SNHG3 is significantly associated with epidermal growth factor receptor 2 (Her-2) and estrogen receptor (ER) status in breast cancer." (PMID 32802874, 2020). "Although we proved the roles of CAF-secreted exosomal SNHG3 signaling pathway in breast cancer development in vitro and in vivo, genetic mutation may still need to offer direct evidence." (PMID 31956955, 2020). "The results collectively demonstrate that STAT3 is essential to the regulating SNHG3 expression in breast cancer cells." (PMID 41042421, 2025). "STAT3 has been shown to regulate SNHG3 expression in breast cancer cells, positioning it as a potential therapeutic target for inhibiting SNHG3." (PMID 41042421, 2025). "In breast cancer, another key lnc-RNAs, SNHG3 (small nucleolar RNA host gene 3), is released via exosomes by CAFs." (PMID 40496868, 2025). "In vivo studies demonstrate silencing SNHG3 reduces breast cancer liver metastasis and gastric cancer lung metastasis." (PMID 41042421, 2025). "Exosomes from CAFs with reduced SNHG3 expression suppressed glycolysis metabolism and cell proliferation in breast cancer cells, while exosomes from CAFs with increased SNHG3 expression enhanced glycolysis metabolism and cell proliferation." (PMID 41042421, 2025). "Annotated lncRNAs already implicated in breast cancer (DSCAM-AS1, NEAT1, SNHG3, ZFAS1) also had a significant (FDR ≤ 0.3) effect, indicating the screen was able to identify functional lncRNAs." (PMID 38745269, 2024). "In breast cancer (BC), SNHG3's role was investigated, revealing its significant expression in BC tissues and its promotion of cell proliferation and metastasis." (PMID 39349640, 2024). "SNHG3, originating from CAFs, functions as a “molecular sponge,” sequestering miR-330 and thereby enhancing the glycolytic activity in breast cancer cells by interacting with PKM." (PMID 39717771, 2024). "For instance, TUG1 within CAF-derived EVs boosts glycolysis in liver cancer, while SNHG3 enhances this process in breast cancer, and NNT-AS1 does so in pancreatic cancer." (PMID 39717771, 2024). "Here, we report that small nucleolar RNA host gene 3 (SNHG3) is a key regulator of breast cancer progression." (PMID 37348024, 2023). "In vitro and in vivo CAFs-secreted exosomal SNHG3 knockdown strategies demonstrated a reversal of the metabolic reprogramming, leading to a decreased breast cancer cell glycolysis and growth." (PMID 35955480, 2022). "Further, SNHG3 silencing led to breast cancer cell growth inhibition both in vitro and in vivo and it was found to act as sponge for miR-154-3p regulating Notch signaling." (PMID 36139687, 2022). "Collectively, CAFs-secreted exosomal SNHG3 resulted in a decrease in mitochondrial oxidative phosphorylation and an increase in glycolysis carboxylation, leading to an increased breast cancer cell growth." (PMID 35955480, 2022). "For instance, SNHG3 stimulates breast cancer cell malignant behaviors through the miR-186-5p/ZEB1 axis." (PMID 35123415, 2022). "There have been few studies conducted on these specific lncRNAs, however, there have been some studies on the function of SNHG3 in breast cancer." (PMID 35855425, 2022). "SNHG3 promotes migration, invasion, and epithelial-mesenchymal transition of breast cancer cells through the miR-186-5p/ZEB1 axis." (PMID 34277410, 2021). "On the contrary, a study conducted to determine the role of SNHG3 in breast cancer in a nude mouse model demonstrated that SNHG3 promotes cancer proliferation and metastasis by functioning as a miR-326 sponge." (PMID 34885213, 2021).